ESCO2 (establishment of sister chromatid cohesion N-acetyltransferase 2)
Description:
Acetyltransferase required for the establishment of sister chromatid cohesion. Couples the processes of cohesion and DNA replication to ensure that only sister chromatids become paired together. In contrast to the structural cohesins, the deposition and establishment factors are required only during the S phase. Acetylates the cohesin component SMC3.
Synonyms: EFO2; EFO2p; hEFO2; 2410004I17Rik; JHS; RBS
Tractability: PROTAC: ubiquitination databases record sites on it.
Gene: Protein-coding gene on chromosome 8 (27,771,949 to 27,812,640, forward strand). Ensembl gene ENSG00000171320.
Subcellular location: Nucleus; Chromosome
Subcellular location (Human Protein Atlas): Nucleoplasm; Cell Junctions; Golgi apparatus
Pathways (Reactome):
Cell Cycle: Establishment of Sister Chromatid Cohesion
Gene Ontology:
Molecular function: acetyltransferase activity; protein binding; protein-lysine-acetyltransferase activity; N-acetyltransferase activity; L-lysine N-acetyltransferase activity, acting on acetyl phosphate as donor
Biological process: post-translational protein acetylation; regulation of DNA replication; sister chromatid cohesion
Cellular component: chromatin; chromosome; nucleoplasm; nucleus; chromocenter; pericentric heterochromatin; site of double-strand break; XY body
Genetic constraint (gnomAD): Loss-of-function variants: 44 observed, 55.83 expected, observed/expected ratio (o/e) 0.79, 90% interval 0.62 to 1.01. The upper end of that interval is the gene's LOEUF score, 1.01, which puts it in group 4 of 6, group 1 being the genes least tolerant of losing a copy. Missense variants: 639 observed, 672.35 expected, observed/expected ratio (o/e) 0.95, 90% interval 0.89 to 1.01. Synonymous variants: 215 observed, 236.07 expected, observed/expected ratio (o/e) 0.91, 90% interval 0.81 to 1.02.
Gene-disease validity (ClinGen):
ClinGen rates the evidence that ESCO2 causes each of these diseases.
Roberts-SC phocomelia syndrome (autosomal recessive): Definitive. A rare genetic syndrome with an autosomal recessive pattern of inheritance.
Homologues: Orthologues: chimpanzee ESCO2 (99% identical), macaque ESCO2 (94% identical), rabbit ESCO2 (79% identical), dog ESCO2 (75% identical), guinea pig ESCO2 (70% identical), mouse Esco2 (69% identical), rat AABR07057438.1 (69% identical), rat Esco2 (69% identical), rat Esco2-ps2 (69% identical), tropical clawed frog esco2 (40% identical), zebrafish esco2 (37% identical). Paralogues in human: ESCO1 (32% identical), REV1 (13% identical), POLI (10% identical), POLK (9% identical), POLH (8% identical).
Diseases named in the same sentence as ESCO2 in open-access papers:
ESCO2 is named in the same sentence as 46 diseases in open-access papers, as found by Europe PMC text mining. Sharing a sentence is not in itself a finding about the gene and the disease. The quoted sentences say what the papers report.
Roberts syndrome (38 papers, 2009 to 2025). "Previous studies on ESCO2 have revealed that human ESCO2 mutations result in Roberts syndrome, an inherited developmental disorder characterized by SCC defects and aberrant transcriptional acetylation." (PMID 40657363, 2025). "Cornelia de Lange syndrome/CdLS (individuals that harbor clinical mutations of cohesin or cohesin deposition gene) and Roberts syndrome/RBS (individuals that harbor clinical ESCO2 mutation) are severe developmental maladies." (PMID 35456431, 2022). "Mechanistically, Roberts syndrome has been linked to mutations in ESCO2 gene, which encodes a cohesin acetyltransferase and modulator of double strand break repair." (PMID 35454109, 2022). "In humans, homozygous mutations in Esco2 cause a rare developmental disorder called Roberts syndrome, but to our knowledge, germ cell development of patients has never been investigated." (PMID 32051254, 2020). "Roberts Syndrome (RBS, also called SC phocomelia syndrome) is caused by bi-allelic mutations in ESCO2." (PMID 31935221, 2020). "To obtain a catalytic-deficient enzyme, we also introduced the missense mutation W539G in ESCO2, which occurs frequently in Roberts Syndrome (RBS) patients." (PMID 30779731, 2019). "Another genetic disorder with a related phenotype is Roberts syndrome, caused by mutations in the ESCO2 gene." (PMID 30067223, 2018). "Roberts syndrome (RBS) is a human developmental disorder caused by mutations in the cohesin acetyltransferase ESCO2." (PMID 26729373, 2016). "Roberts Syndrome is caused by a mutation in ESCO2, a gene involved in chromosome separation, cell division, and DNA repair." (PMID 26043938, 2015). "A zebrafish model of Roberts syndrome indicates that ESCO2 loss prevents normal development by disrupting the cell cycle." (PMID 26043938, 2015). "In humans, point mutations in the Eco1 homolog ESCO2 lead to congenital abnormalities exemplified by Roberts syndrome (RBS)." (PMID 23750584, 2013). "Since the exact same ESCO2 mutation can cause Roberts or SC Phocomelia, it has been proposed that both be termed Roberts Syndrome, which would then cover the entire spectrum of pathology." (PMID 21637801, 2011). "In this study we investigate ESCO2-deficient immortalized skin fibroblasts from a Roberts syndrome patient in comparison to isogenic ESCO2 complemented cell lines to document the cellular phenotype of ESCO2-deficient cells." (PMID 19738907, 2009). "Roberts syndrome is a rare autosomal recessive multisystem developmental disorder that is caused by mutations in ESCO2." (PMID 19738907, 2009). "ESCO2 was first reported in Roberts syndrome, whose inactivation mutation causes Roberts Syndrome." (PMID 38605349, 2024). "Roberts syndrome (RBS) is a recessive cohesinopathy caused by homozygous mutation in ESCO2." (PMID 34202641, 2021). "Additionally, mutations in three Cohesin subunits (SMC1α, SMC3, RAD21) and in one Cohesin-interacting protein (NIPBL) have been found causal for CdLS, whereas mutations in ESCO2 are responsible for Roberts syndrome/SC Phocomelia (OMIM# 269000)." (PMID 33263776, 2021). "Roberts syndrome is a human developmental disorder caused by mutations in the ESCO2 gene." (PMID 24098154, 2013). "Mutations in both copies of ESCO2 are associated with the human disease Roberts syndrome (RBS)." (PMID 23050226, 2012). "Transcriptional dysregulations that arise in response to ESCO2 mutation in humans result in severe developmental abnormalities and intellectual disabilities termed Roberts syndrome (RBS)." (PMID 35736360, 2022). "Moreover, mutations in ESCO2 gene cause Roberts Syndromes with a predisposition to cancer." (PMID 30779731, 2019). "Likewise, Roberts Syndrome in humans has been linked to point mutations in ESCO2." (PMID 25848842, 2015). "Mutations in ESCO2 lead to Roberts syndrome (RBS), which is associated with a variety of defects including growth retardation, limb reduction/asymmetric limb growth, cleft lip/palate and missing fingers/toes." (PMID 25848842, 2015).
Roberts syndrome (continued). "Mutations in the human homolog of ECO1 (ESCO2/EFO2), or in genes that encode cohesin subunits, result in severe developmental abnormalities and intellectual disabilities referred to as Roberts syndrome and Cornelia de Lange syndrome, respectively." (PMID 35736360, 2022). "In further support of ESCO2 playing a role in tumorigenesis, some Roberts Syndrome patients (RBS) who carry autosomal recessive germline inactivating mutations in ESCO2, display early-onset cancer predisposition." (PMID 35994499, 2022). "Roberts syndrome (RBS, OMIM 268300) is a rare autosomal recessive disorder caused by variants in the establishment of the cohesion 1 homolog 2 (ESCO2) gene." (PMID 35093090, 2022). "In humans, mutations in ECO1 orthologs (termed ESCO1/EFO1 and ESCO2/EFO2) collectively correlate with numerous forms of cancer, including melanoma and prostate cancer, and a severe developmental abnormality called Roberts Syndrome (RBS)." (PMID 33373396, 2020). "Roberts syndrome (RBS; MIM #268300), also known as Pseudothalidomide syndrome, is a rare autosomal recessive disorder caused by mutations in ESCO2 gene." (PMID 31388035, 2019). "These cohesion defects resemble the ones observed in metaphase lymphoblasts from individuals affected by Roberts syndrome (RBS), another rare autosomal recessive disease due to mutations in the ESCO2 gene." (PMID 30469382, 2018). "Roberts syndrome (RBS) is caused by recessive mutations exclusively in ESCO2." (PMID 26044958, 2015). "Inactivating mutations in ESCO2 cause Roberts Syndrome/SC Phocomelia (RBS/SC)." (PMID 21637801, 2011). "Nevertheless, to explore the function of the human ESCO2 protein, there is a need for functionally corrected cell lines from Roberts syndrome patients." (PMID 19738907, 2009). "Roberts syndrome (RBS) is a rare autosomal recessive disorder caused by variations in the ESCO2 gene; however, prenatal diagnosis of RBS has never been reported in Chinese families." (PMID 35093090, 2022). "Since ESCO2 has been identified as the gene defective in the rare autosomal recessive cohesinopathy Roberts syndrome (RBS), cells from RBS patients can be used to elucidate the role of ESCO2." (PMID 19738907, 2009). "Interestingly, amongst viable (majority die in utero or postnatally) Roberts Syndrome (RBS) patients, which are homozygous null of ESCO2, they also display reduced SCC and early onset tumor occurrence; supporting the fact that reduced SCC is tumor-promoting across species." (PMID 35994499, 2022). "Mutations in ESCO2, one of two establishment of cohesion factors necessary for proper sister chromatid cohesion (SCC), cause a spectrum of developmental defects in the autosomal-recessive disorder Roberts syndrome (RBS), warranting in vivo analysis of the consequence of cohesion dysfunction." (PMID 26044958, 2015).
gastric cancer (5 papers, 2019 to 2025). A primary or metastatic malignant neoplasm involving the stomach. "Moreover, ESCO2 knockdown inhibits cell proliferation and induces apoptosis in human gastric cancer cells." (PMID 35355509, 2022).
glioma (4 papers, 2021 to 2025). A benign or malignant brain and spinal cord tumor that arises from glial cells (astrocytes, oligodendrocytes, ependymal cells). "Among these LARs that showed increased expression with increasing WHO grade in both the CGGA and TCGA datasets, HDAC1 is the best-studied LAR in glioma, whereas the potential functions of ESCO2, KAT1, LEF1, and SLC16A10 are unreported in this cancer." (PMID 33718432, 2021).
melanoma (4 papers, 2007 to 2020). A malignant, usually aggressive tumor composed of atypical, neoplastic melanocytes. "ESCO2 is an acetyltransferase, which is required for cohesion acetylation and the establishment of sister chromatid cohesion in the S phase, and has been found to be upregulated in melanoma." (PMID 29642861, 2018).
Warsaw breakage syndrome (3 papers, 2015 to 2025). A syndrome mainly characterized by severe growth retardation and microcephaly. "Roberts syndrome/SC phocomelia (RBS), and Warsaw Breakage syndrome (WABS) are two recessive cohesinopathies, caused by homozygous mutations in single genes, ESCO2 and DDX11/CHLR1, respectively." (PMID 27636994, 2016).
bladder cancer (2 papers, 2019 to 2024). "To confirm ESCO2 as a potential pan-cancer biomarker, we further validated the carcinogenesis of ESCO2 in bladder cancer cell lines." (PMID 38605349, 2024).
breast carcinoma (2 papers, 2023 to 2025). "ESCO2, a potential key regulator of the cell cycle, is implicated in cancer development; however, its specific role and mechanisms in breast cancer remain poorly understood." (PMID 40708936, 2025). "Through cell functional experiments, we further determined the regulatory potential and mechanisms of ESCO2 in the cell cycle and apoptosis of breast cancer cells." (PMID 40708936, 2025). "The CCK-8 results demonstrated that compared to the vector control group, ESCO2 overexpression accelerated the proliferation rate in both breast cancer cell lines." (PMID 40708936, 2025). "Our study revealed significant variations in ESCO2 expression at both mRNA and protein levels among different breast cancer cell lines." (PMID 40708936, 2025). "In contrast, our findings indicate that knockdown of ESCO2 leads to an extended G2/M phase in the cell cycle of breast cancer cells." (PMID 40708936, 2025). "We conducted a comprehensive bioinformatics analysis of breast cancer samples from the GEO database, which gradually identified ESCO2 as a potential key molecule in the cell cycle." (PMID 40708936, 2025). "Our flow cytometry analysis revealed that overexpression of ESCO2 increases the S phase in breast cancer cells, which is consistent with previous studies." (PMID 40708936, 2025). "RT-qPCR results revealed that ESCO2 mRNA was expressed at low levels in the normal breast cell line MCF10A but was significantly upregulated in breast cancer cell lines BT-474, MDA-MB-231, and MDA-MB-468." (PMID 40708936, 2025). "To further investigate the molecular mechanisms by which ESCO2 affects the cell cycle and apoptosis in breast cancer cells, we assessed the expression changes of related proteins." (PMID 40708936, 2025). "ESCO2 interacted with multiple cell cycle-related genes and was significantly overexpressed in breast cancer." (PMID 40708936, 2025). "To further validate the effect of ESCO2 on DNA synthesis in breast cancer cells, we examined cell proliferation changes after ESCO2 overexpression using the CCK-8 assay." (PMID 40708936, 2025). "To assess the functional consequences of ESCO2 in breast cancer cells, we used lentiviral transduction to either overexpress or knock down its expression, and subsequently examined its effects on cell cycle progression and apoptosis." (PMID 40708936, 2025). "In summary, our study demonstrates that ESCO2 is highly expressed in breast cancer and serves as a potential master regulator of cell cycle progression in breast cancer cells." (PMID 40708936, 2025). "This study first predicted the potential pathways through which ESCO2 might function using GSEA, and then examined the differential expression of ESCO2 in various breast cancer cell lines compared to normal breast cells." (PMID 40708936, 2025). "ESCO2 expression was further investigated in breast cancer cell lines." (PMID 40708936, 2025). "Therefore, siP53 successfully reversed the cell cycle arrest and apoptosis induced by ESCO2 knockdown in breast cancer cells." (PMID 40708936, 2025). "In addition, a recent bioinformatics study demonstrated the potential significance of the STAT1/ESCO2 pathway in breast cancer." (PMID 37968576, 2023). "Therefore, overexpression of ESCO2 promotes DNA replication in breast cancer cells." (PMID 40708936, 2025). "Interestingly, microarray analysis demonstrated that STAT1 is co-expressed with ESCO2 and may regulate its transcription in breast cancer." (PMID 37968576, 2023).
cervical cancer (2 papers, 2019 to 2021). A primary or metastatic malignant neoplasm involving the cervix. "The remaining 10 genes (i.e., YJEFN3, SPATA5L1, C5orf55, PPM1A, IMMP1L, ZNF330, PPIP5K2, ESCO2, FICD, and ZNF225) are not directly reported to be related to the survival risk of cervical cancer in previous literature." (PMID 34149809, 2021).
colon cancer (2 papers, 2019 to 2024). "ESCO2 has been shown to prevent cancer metastasis in a recent trial on colon cancer, which is consistent with the results of our bioinformatics research." (PMID 38605349, 2024).
craniosynostosis (2 papers, 2019 to 2025). Craniosynostosis is defined as the premature fusion of one or more cranial sutures leading to secondary distortion of skull shape resulting in skull deformities with a variable presentation. "Craniosynostosis is a distinctive sign of BGS as it has been reported in 82% (9/11) of BGS patients with RECQL4 alterations but in RBS with ESCO2 pathogenic variants only in the 2 patients herein described and in 2 patients of the literature, for whom no details or images are provided." (PMID 31192177, 2019).
hepatocellular carcinoma (2 papers, 2019 to 2025). A malignant tumor that arises from hepatocytes. "Consistent with the results of bulk RNA sequencing data analysis, cell proliferation-associated pathways, such as E2F targets, G2M checkpoint, and MYC targets signaling, were significantly enriched in ESCO2-positive hepatoma cells." (PMID 40657363, 2025). "The results presented above collectively indicated that ESCO2 knockdown suppressed the proliferative capacity of hepatoma cell lines." (PMID 40657363, 2025). "We first validated the knockdown efficiency of ESCO2-siRNA in hepatoma cell lines." (PMID 40657363, 2025).
lung carcinoma (2 papers, 2019 to 2022). "However, ESCO2 resides on chromosome 8p21, and in many human cancers, including liver, breast, prostate, ovarian, uterine, colorectal, bladder and lung cancers, recurrent deletion of genes on the p arm of chromosome 8 is observed." (PMID 35994499, 2022).
acute myeloid leukemia (1 paper, 2024). Acute myeloid leukemia (AML) is a group of neoplasms arising from precursor cells committed to the myeloid cell-line differentiation. "In our study, 30 of 33 cancer types exhibited considerably greater levels of ESCO2 expression in tumor tissue using TCGA and GTEx databases, whereas acute myeloid leukemia (LAML) exhibited significantly lower levels." (PMID 38605349, 2024).
Baller-Gerold syndrome (1 paper, 2021). Baller-Gerold syndrome is characterized by the association of coronal craniosynostosis with radial ray anomalies (oligodactyly, aplasia or hypoplasia of the thumb, aplasia or hypoplasia of the radius). "In humans, ESCO2, TBX5, and RECQL4 cause Roberts, Holt–Oram, and Baller–Gerold syndromes, respectively." (PMID 34249098, 2021).
colorectal cancer (1 paper, 2023). A primary or metastatic malignant neoplasm that affects the colon or rectum. "Analyses of TCGA and GTEx databases showed that the expression level of ESCO2 in colorectal cancer tissues was higher than that in normal tissues." (PMID 37377435, 2023). "Taken together, these results suggest that ESCO2 increases the resistance of colorectal cancer cells to oxaliplatin by promoting DSB repair efficiency." (PMID 37377435, 2023). "The role of ESCO2 in colorectal cancer cells identified in this study provides a novel molecular explanation for CRC chemoresistance." (PMID 37377435, 2023). "Collectively, these results suggest that ESCO2 promotes chemotherapeutic drug-induced DDR in colorectal cancer cells." (PMID 37377435, 2023). "Therefore, we tested ESCO2 expression levels in three colorectal cancer cell lines (HCT116, LOVO and RKO) and two normal colorectal epithelial cell lines (NCM460 and FHC)." (PMID 37377435, 2023). "Depletion of ESCO2 renders colorectal cancer cells hypersensitive to chemotherapeutic drugs." (PMID 37377435, 2023). "To further investigate the role of ESCO2 in the DDR in colorectal cancer, we stably knocked down ESCO2 in HCT116 cells (ESCO2 KD HCT116) and monitored γH2AX foci, a biomarker of DSB damage, using an immunofluorescence assay 12 h after bleomycin treatment." (PMID 37377435, 2023). "TCGA analysis showed that the expression level of ESCO2 positively correlated with 53BP1 and BRCA1 in colorectal cancer samples." (PMID 37377435, 2023). "Furthermore, ESCO2 promotes the formation of 53BP1 foci to DSB sites by stabilizing cohesin complex and is essential for resistance to chemotherapy in colorectal cancer cells (CRC)." (PMID 37377435, 2023).